RNU6-7 (RNA, U6 small nuclear 7)
Synonyms: U6-7
Gene: Small nuclear RNA gene on chromosome 14 (32,202,045 to 32,202,151, forward strand). Ensembl gene ENSG00000201654.
Gene Ontology:
Molecular function: U4 snRNA binding
Biological process: formation of quadruple SL/U4/U5/U6 snRNP; spliceosomal tri-snRNP complex assembly
Cellular component: U4/U6 x U5 tri-snRNP complex; U6 snRNP
Homologues: Orthologues: chimpanzee U6 (100% identical), guinea pig U6 (100% identical), mouse Gm23296 (100% identical), mouse Gm24859 (100% identical), pig U6 (100% identical), rabbit U6 (100% identical), rat U6 (100% identical). Paralogues in human: RNU6-8 (100% identical), RNU6-1 (99% identical), RNU6-2 (99% identical), RNU6-3P (99% identical), RNU6-4P (99% identical), RNU6-5P (99% identical), RNU6-6P (99% identical), RNU6-9 (99% identical), RNU6-11P (98% identical), RNU6-12P (98% identical), RNU6-13P (98% identical), RNU6-17P (98% identical), and 1288 more.